MUC4 (mucin 4, cell surface associated)
Diseases named in the same sentence as MUC4 in open-access papers (continued):
Sharing a sentence is not in itself a finding about the gene and the disease.
Diarrhea (2 papers, 2019 to 2020). Abnormally increased frequency (usually defined as three or more) loose or watery bowel movements a day. "Previous studies have shown that pigs can be susceptible (SS), partially susceptible (SR) or resistant (RR) to developing ETEC-F4 diarrhoea depending on the MUC4 allele." (PMID 31346463, 2019). "Alternatively, in experiments that require pigs to be predisposed to developing ETEC-F4 diarrhoea, polymerase chain reaction-restriction fragment length polymorphism testing that targets the MUC4 gene has been used to determine which pigs are susceptible." (PMID 31346463, 2019). "The hypotheses tested in this study were that pigs with MUC4+ allele would develop more ETEC-F4 diarrhoea than pigs with the MUC4– allele, sequencing of the MUC4– allele would provide a more robust prediction of genotype, and feeding ZnO would reduce PWD." (PMID 31346463, 2019). "This experiment confirmed that ETEC-F4 diarrhoea was significantly higher in MUC4+ pigs, as determined by sequence analysis of the gene compared to MUC4– pigs following experimental ETEC infection." (PMID 31346463, 2019). "The percentage of pigs that developed diarrhoea following infection was higher (P = 0.05) in MUC4+ pigs compared to MUC4– pigs (50% vs. 26.8%, respectively)." (PMID 31346463, 2019). "This is further supported by another study, where average faecal scores, days with diarrhoea and total E. coli shedding were higher (P < 0.001) in MUC4+ pigs compared to MUC4– pigs." (PMID 31346463, 2019). "A DNA marker-based test targeting the mucin 4 gene (MUC4) that encodes F4 fimbria receptor identified pigs as either fully susceptible (SS), partially or mildly susceptible (SR), and resistant (RR) to developing ETEC-F4 diarrhoea." (PMID 31346463, 2019). "Furthermore and due to the low number of MUC4+ pigs the suppression of ETEC-F4 diarrhoea in pigs fed ZnO could also be due to the low number of genetically susceptible pigs." (PMID 31346463, 2019). "Having done this, we then hypothesised that pigs with the F4 receptor (MUC4+ allele) would develop more ETEC-F4 diarrhoea than pigs without the F4 receptor (MUC4– allele) when experimentally infected with ETEC-F4." (PMID 31346463, 2019).
ductal adenocarcinoma (2 papers, 2019 to 2022). "Further, the importance of MUC4 expression was identified in invasive ductal carcinoma (ICD) of the pancreas." (PMID 35255004, 2022). "Both membrane-bound (MUC1, MUC3, MUC4) and secreted mucins (MUC2, MUC5AC, MUC5B, MUC6) are upregulated in ductal adenocarcinoma of the breast." (PMID 30682816, 2019).
dysplasia (2 papers, 2021 to 2023). A usually neoplastic transformation of the cell, associated with altered architectural tissue patterns. "On the other hand, MUC4 was found to be overexpressed in squamous metaplasia and dysplasia." (PMID 36980526, 2023).
gallstones (2 papers, 2021 to 2022). Solid crystalline precipitates in the biliary tract, usually formed in the gallbladder, resulting in the condition of cholelithiasis. "Studies have shown that oral pathogenic bacteria affect gallbladder movement and the expression of mucin genes (MUC1, MUC3, and MUC4) through the immune regulation mechanism, regulate cholesterol metabolism and promote the formation of gallstone." (PMID 35651949, 2022). "These loci are located in seven different genes, including SLC4A5, MUC4, FTO, NPC1 and FXYD2 genes that may increase the risk of gallstone in the Tibetan population, while CFTR and ADCY2 genes that reduce the risk of gallstone in the Tibetan population." (PMID 35651949, 2022).
invasive carcinoma (2 papers, 2014 to 2020). A carcinoma that is not confined to the epithelium, and has spread to the surrounding stroma. "MUC1 is known to be associated with a higher risk of invasive carcinoma, as is MUC4." (PMID 33145018, 2020). "In summary, intense expression of MUC4 was observed in normal epithelium and its progressive loss in carcinoma in situ/papillary carcinoma stage which was followed by complete loss during high and low grade invasive carcinoma." (PMID 24671186, 2014). "Further MUC4 expression was either absent or present focally in low grade and high grade invasive carcinoma cases from tissues." (PMID 24671186, 2014).
mesothelioma (2 papers, 2017 to 2018). A usually malignant and aggressive neoplasm of the mesothelium which is often associated with exposure to asbestos. "Among the negative mesothelioma markers, MUC4, CEA, Claudin 4, TTF-1, and Napsin-A showed 100% sensitivity, p40 showed 95.4%, P63 showed 76.9%, and CK5/6 showed 69.2%." (PMID 29317712, 2018).
mucinous adenocarcinoma (2 papers, 2014 to 2017). An invasive adenocarcinoma composed of malignant glandular cells which contain intracytoplasmic mucin. "Contrastingly, infiltrating lobular carcinoma (ILC) and mucinous carcinoma expressed MUC4 faintly, while IDC exhibited intermediate expression levels." (PMID 29281999, 2017). "In spite of the small number of cases reported in this study (IMPC, n = 8, IDC, n = 10, ILC, n = 20; mucinous carcinoma, n = 10), the data showed a statistically significant increase in mRNA MUC4 levels in IMPC with respect to those in mucinous carcinoma (P = 0.0164)." (PMID 29281999, 2017). "Histological analysis of this cohort showed that 79.6% were IDC, 9,8% infiltrating lobular carcinoma (ILC), 5.3% mucinous carcinoma and 5.3% IMPC.We observed that IMPC is the histological entity with the highest MUC4 expression." (PMID 29281999, 2017). "Interestingly, our results clearly show that MUC4 is overexpressed in IMPC as compared to IDC, ILC and mucinous carcinoma." (PMID 29281999, 2017). "Similarly, mucinous adenocarcinomas were also found to negative for MUC4 expression." (PMID 24671186, 2014).
mucinous tumors (2 papers, 2020 to 2022). "Similarly, non-mucinous tumors, which were 66%, also had low to moderate levels of MUC4, while 34% of CRC patients had upregulation of MUC4." (PMID 35255004, 2022). "In another study, 66% of non-mucinous tumors had low to moderate levels of MUC4, while 34% of CRC had higher MUC4 in it." (PMID 32168759, 2020).
myoepithelial tumor (2 papers, 2019 to 2025). A benign or malignant tumor characterized by the presence of cells that show myoepithelial differentiation. "MUC4 is usually negative in myoepithelial tumors but is positive in 29% (five of 17) of OFMT cases." (PMID 40151688, 2025). "At the time of the initial diagnosis, the concept of primary myoepithelial tumors of soft tissue and bones was not yet well established and little was known on the molecular background of SEF and the MUC4 immunohistochemistry—nowadays easy to apply to verify this diagnosis—was not yet available." (PMID 31049020, 2019).
neuroblastoma (2 papers, 2024 to 2025). Neuroblastoma (NB) is the most common solid, extracranial childhood tumor. "In 58 whole exome sequencing (WES) and 48 whole transcriptome sequencing (WTS) samples of MYCN non-amplified neuroblastoma (NB), recurrent mutations were observed in genes like MUC4 and RBMXL3." (PMID 39823827, 2025). "The frequencies of MUC4, MUC16, and KMT2C have also been substantially high in previous studies, implying their roles in neuroblastoma development." (PMID 39338204, 2024). "Moreover, the frequency of MUC4 and MUC16 mutations in our study was considerably higher than that reported in a previous study on MYCN non-amplified neuroblastoma (70% vs. 26% for MUC4 and 38% vs. 14% for MUC16)." (PMID 39338204, 2024).
ossifying fibromyxoid tumor (2 papers, 2020 to 2023). A rare soft tissue tumor of uncertain lineage characterized by the presence of neoplastic spindle to round cells forming cords in a fibromyxoid stroma. "The present of bony tissue in the tumor raises the possibility of ossifying fibromyxoid tumor (OFMT), as some OFMTs can be at least focally positive for MUC4 expression." (PMID 32164724, 2020). "Notably, MUC4 expression can also be seen in SEF, synovial sarcomas, ossifying fibromyxoid tumors, epithelioid gastrointestinal stromal tumors and myoepithelial carcinomas." (PMID 32164724, 2020).
paroxysmal nocturnal haemoglobinuria (2 papers, 2023 to 2026). "This study aimed to investigate the role and clinical significance of MUC4 gene mutations in thrombotic events in patients with classic paroxysmal nocturnal hemoglobinuria(PNH)patients." (PMID 37749036, 2023).
polyp (2 papers, 2016 to 2017). A usually exophytic mass attached to the underlying tissue by a broad base or a thin stalk. "The polyp section examined showed a loss of MUC4 expression, concurrent with an increased expression (cytoplasmic/nuclear) of β-catenin relative to the normal colon section." (PMID 27551331, 2016). "Of all mucins examined, the expression of MUC4 was significantly altered by polyp site (p = 0.037) and tobacco consumption (p = 0.021)." (PMID 27705923, 2017). "Considering the high clinical utility of the appropriate polyp classification, in this study, we evaluated the potential of colonic mucins (MUC1, MUC4, MUC17, MUC2, MUC5AC, and MUC6) and associated glycans (Tn/STn-MUC1 and CA19-9) for differentiating SSA/P from HP and TA." (PMID 27705923, 2017). "Interestingly, MUC4 was the only mucin whose expression was significantly impacted by the site of the polyp, suggesting the role of colonic microenvironment in the regulation of this mucin." (PMID 27705923, 2017).
primary sclerosing cholangitis (2 papers, 2008 to 2016). "In bile, MUC4 protein was detected in 27% of BTC and 29% of primary sclerosing cholangitis (PSC) cases, but not in other benign and malignant biliary diseases (P<0.01 and P=0.06)." (PMID 18475301, 2008).
prostate adenocarcinoma (2 papers, 2014 to 2018). "During the study, they observed that the expression level of MUC4 was much lower in prostatic adenocarcinoma tissue (CaP) compared to adjacent normal/benign prostate tissue (N/BPH)." (PMID 24671186, 2014).
prostate tumor (2 papers, 2004 to 2009). "Using PAC120, a xenograft of a human hormone-dependent prostate tumour, and its hormone-independent variants, we analysed the expression of mucins (MUC1, MUC2, MUC4, MUC5AC, MUC5B, MUC6) by immunohistochemistry or reverse transcriptase (RT)–PCR." (PMID 14760390, 2004). "In light of our findings it would be interesting to determine whether prostate metastases similarly regain MUC4 expression and contribute to prostate tumor cell aggressiveness." (PMID 19761616, 2009). "Interestingly, a recent study found that MUC4 expression levels in primary prostate tumors is lower on average than in normal or benign hyperplastic tissue, although patient-matched tissues were not employed." (PMID 19761616, 2009).
rhabdomyosarcoma (2 papers, 2023 to 2024). A rare aggressive malignant mesenchymal neoplasm arising from skeletal muscle. "An example of this is the frequent coexpression of pankeratin and ALK in FET::TFCP2 fusion aggressive rhabdomyosarcomas and the frequent expression of EMA and keratins (in addition to occasional ALK, MUC4, etc.)in FET::CREB fusion intra-abdominal neoplasms." (PMID 39249507, 2024).
soft tissue tumors (2 papers, 2016 to 2026). "Among other soft tissue tumors, MUC4 is a sensitive and useful marker for identifying only sclerosing epithelioid fibrosarcoma, which has similarities to LGFMS." (PMID 27247823, 2016).
spindle cell neoplasm (2 papers, 2020 to 2026). A benign or malignant neoplasm characterized by the presence of neoplastic spindle cells. "MUC4-positive fibroblastoma is a newly characterized fibroblastic neoplasm, typically presenting as a bland spindle cell tumor with diffuse cytoplasmic MUC4 expression, nuclear β‐catenin positivity, and APC gene alterations." (PMID 41773132, 2026). "MUC4 was performed in 20 myxoid spindle cell neoplasms, of which for six this helped towards the diagnosis of LGFMS." (PMID 33061792, 2020).
Stroke (2 papers, 2019 to 2023). Sudden impairment of blood flow to a part of the brain due to occlusion or rupture of an artery to the brain. "Most importantly, this appears to be mediated by E2, as estrogen supplementation in aged female mice prior to stroke led to enhanced expression of Muc2 and Muc4 in the gut epithelium, similar to that seen in ovary-intact females." (PMID 37910478, 2023). "However, in young female mice, there was a significant increase in mucin genes after stroke (P = .0234 for Muc2 and P = .0434 for Muc4)." (PMID 37910478, 2023). "Interestingly, E2-replaced stroke mice showed higher expression of Muc2 (P = .0156) and Muc4 (P = .0003), compared with the vehicle-treated group." (PMID 37910478, 2023). "Interestingly, gene expression of key components that form the mucus layer, mucin 2 (Muc2), mucin 4 (Muc4) and mucin 13 (Muc13) was decreased only in the older mice, but not in young mice, after stroke." (PMID 31199577, 2019).
thyroid cancer (2 papers, 2012 to 2020). "In thyroid cancer, studies have found that MUC1, MUC4, and MU15 are overexpressed in PTC." (PMID 33489878, 2020).
urothelial carcinoma (2 papers, 2014 to 2025). A malignant neoplasm derived from the transitional epithelium of the urinary tract (urinary bladder, ureter, urethra, or renal pelvis). "Since the loss of MUC4 expression is observed at very early stages, our study indicates that MUC4 loss might be of diagnostic relevance for early detection of urothelial carcinoma." (PMID 24671186, 2014). "Expression of both MUC1 and MUC4, however, are significantly higher in urothelial carcinoma metastatic cases compared to localized UC." (PMID 24671186, 2014). "In majority of the cases, focal expression of MUC4 was observed in urothelial carcinoma (N = 122 or 58%, mean H-score, mean intensity 0) whereas other cases showed mild positivity (N = 89 or 42% cases, mean H-score 0.68±0.14, mean intensity 0.91±0.19)." (PMID 24671186, 2014). "Further studies need to be carried out in urothelial carcinoma to decipher the mechanism of MUC4 downregulation." (PMID 24671186, 2014). "While aberrant changes were observed in expression and localization pattern of MUC1 between benign and malignant cases, significant downregulation of MUC4 was observed during urothelial carcinoma compared to normal and/or benign bladder tissues." (PMID 24671186, 2014). "In this study, we explored the expression profile of transmembrane mucins (MUC1 and MUC4) in urothelial carcinoma tissue sections and three tissue TMAs." (PMID 24671186, 2014). "Additionally, we observed the overexpression of MUC4, a transmembrane mucin associated with metastatic urothelial carcinoma, and CLDN4, a marker linked to more invasive and higher-grade urothelial carcinomas." (PMID 40004083, 2025). "Interestingly, in comparison to urothelial carcinoma that lacks the expression of MUC4, higher percentage of metastatic cases were found to be positive for MUC4." (PMID 24671186, 2014). "Variation of MUC4 expression with grades of Urothelial Carcinoma." (PMID 24671186, 2014). "In comparison to non-neoplastic urothelium, the loss of MUC4 expression was observed during urothelial carcinoma (n = 211, 0.56±0.06)." (PMID 24671186, 2014). "However, re-expression of MUC4 was observed in a subset of metastatic cases of urothelial carcinoma (mean H-score 0.734±0.9)." (PMID 24671186, 2014). "Since the loss of MUC4 expression was observed in non-invasive papillary UC and urothelial CIS cases, the present study suggests that loss of MUC4 might be one of the early events during development of urothelial carcinoma." (PMID 24671186, 2014).
adenosquamous carcinoma (1 paper, 2013). A carcinoma composed of malignant glandular cells and malignant squamous cells. "Indeed, 80–85% of NSCLCs express MUC4, and adeno- and adenosquamous-carcinomas are characterized by high levels of MUC4 expression (68 and 75%, respectively)." (PMID 23630663, 2013).
allergic conjunctivitis (1 paper, 2021). "In the conjunctiva of an experimental allergic conjunctivitis mouse model, the number of filled goblet cells reduced, and MUC5AC and MUC4 mRNA levels decreased by the repeated instillation of allergens." (PMID 34194821, 2021).
anaphylaxis (1 paper, 2025). An acute hypersensitivity reaction that occurs from exposure to an allergen. "However, based on their known biological roles—POTEF in retinal homeostasis, MUC4 in mucin production, and SPATA31A1 in cell differentiation and spermatogenesis —it is unlikely that these genes are directly involved in the pathogenesis of cefaclor‐induced anaphylaxis." (PMID 40974473, 2025).
Anorexia (1 paper, 2016). Lack of desire to eat (loss of appetite). "The outcome of F4+ ETEC/VTEC/EPEC infection in MUC4 RR pigs includes fever, anorexia, depression, weight loss, mild diarrhea, the onset of enteritis in the small intestine and excessive systemic inflammatory responses." (PMID 27424033, 2016).
autoimmune disease (1 paper, 2024). A disorder resulting from loss of function or tissue destruction of an organ or multiple organs, arising from humoral or cellular immune responses of the individual to their own tissue constituents. "What is more, MUC4 is highly associated with SARS-CoV-2 infection, and its subsequent dysregulated immune-inflammatory response plays an important role in the pathogenic mechanisms of autoimmune diseases such as rheumatoid arthritis and systemic lupus erythematosus." (PMID 38400850, 2024).
B-cell lymphoma (1 paper, 2025). "Next, the MUC4 gene is known to be mutated in B-lymphoblastic leukemia, and B-cell lymphoma." (PMID 41296384, 2025). "Although MUC4 is noticed to be recurrently mutated in B-lymphoblastic leukemia, and B-cell lymphoma, the six pathogenic variants in MUC4 were not overlapped, in which four mutations were novel." (PMID 41296384, 2025).
bacterial vaginosis (1 paper, 2016). Infection caused by bacterial overgrowth in the vagina. "In this study we report the changes in membrane bound (MUC1 and MUC4) and gel-forming mucins (MUC5AC and MUC7) relative to the influence of hormones and the presence of the abnormal vaginal flora of bacterial vaginosis." (PMID 27437931, 2016).
bile duct carcinoma (1 paper, 2021). "A positive mucin 4 (MUC4) immunohistochemical method is associated with poor prognosis in bile duct carcinoma." (PMID 33806265, 2021).
bone tumours (1 paper, 2014). "Mucin 4 is among major constituents of mucus, and it has demonstrated that primary bone tumours rarely express MUC4 protein, which correlates to our finding." (PMID 25496518, 2014).
breast invasive carcinoma (1 paper, 2024). "MUC4, RP1L1 and QRICH2 mutations were identified in at least three tumors, and these mutation also existed in breast invasive carcinoma databases (TCGA, Cell 2015; TCGA, Nature 2012)." (PMID 38243319, 2024).
chondrosarcoma (1 paper, 2024). A malignant cartilaginous matrix-producing mesenchymal neoplasm arising from the bone and soft tissue. "In two cases, one SEF and one mesenchymal chondrosarcoma, RNA quality was insufficient for fusion gene analysis, although in the SEF, EWSR1 rearrangement using FISH and MUC4 positivity confirmed the diagnosis." (PMID 38332052, 2024).
chronic gastritis (1 paper, 2015). Inflammation of the stomach that is chronic in nature. "We noticed that 6 somatic variations (ATXN3, PLIN4, PDZD2, MUC4, DMBT1 and DAB1) were simultaneously observed in triple samples of chronic gastritis, primary cancer and PM cancer." (PMID 26330360, 2015).
Cirrhosis (1 paper, 2021). A chronic disorder of the liver in which liver tissue becomes scarred and is partially replaced by regenerative nodules and fibrotic tissue resulting in loss of liver function. "Correlations among FGF3 mutation, MUC4 mutation and cirrhosis." (PMID 35118119, 2021). "However, our results suggested that there were little correlations between gene variations and clinical characteristics except that cirrhosis tended to occur in FGF3 and MUC4 mutation groups." (PMID 35118119, 2021). "Cirrhosis tended to occur in FGF3 and MUC4 mutation groups (p = 0.019 and 0.011, respectively)." (PMID 35118119, 2021).